SLC16A7 (solute carrier family 16 member 7)
Description:
Proton-coupled monocarboxylate symporter. Catalyzes the rapid transport across the plasma membrane of monocarboxylates such as L-lactate, pyruvate and ketone bodies, acetoacetate, beta-hydroxybutyrate and acetate. Dimerization is functionally required and both subunits work cooperatively in transporting substrate.
Synonyms: MCT2
Tractability: Antibody: UniProt places it where antibodies can reach, with high confidence; its Gene Ontology location is reachable by antibodies, with high confidence; UniProt predicts a signal peptide or a membrane-spanning region; the Human Protein Atlas places it where antibodies can reach. PROTAC: ubiquitination databases record sites on it; its protein half-life has been measured; a small molecule that binds it is known.
Target class: SLC16 family of monocarboxylate transporters; Electrochemical transporter; SLC superfamily of solute carriers; Transporter
Gene: Protein-coding gene on chromosome 12 (59,596,027 to 59,789,855, forward strand). Ensembl gene ENSG00000118596.
Subcellular location: Cell membrane; Basolateral cell membrane; Cytoplasm
Subcellular location (Human Protein Atlas): Plasma membrane; Nucleoplasm
Pathways (Reactome):
Transport of small molecules: Proton-coupled monocarboxylate transport
Gene Ontology:
Molecular function: identical protein binding; lactate transmembrane transporter activity; protein binding; pyruvate transmembrane transporter activity; symporter activity; pyruvate secondary active transmembrane transporter activity; monocarboxylic acid transmembrane transporter activity; secondary active monocarboxylate transmembrane transporter activity; transmembrane transporter activity
Biological process: lactate transmembrane transport; pyruvate transmembrane transport; plasma membrane lactate transport; transport across blood-brain barrier; monocarboxylic acid transport; transmembrane transport
Cellular component: plasma membrane; basolateral plasma membrane; cytoplasm; glutamatergic synapse; hippocampal mossy fiber to CA3 synapse; membrane; parallel fiber to Purkinje cell synapse; postsynaptic density membrane; Schaffer collateral - CA1 synapse
Genetic constraint (gnomAD): Loss-of-function variants: 28 observed, 31.13 expected, observed/expected ratio (o/e) 0.9, 90% interval 0.67 to 1.23. The upper end of that interval is the gene's LOEUF score, 1.23, which puts it in group 5 of 6, group 1 being the genes least tolerant of losing a copy. Missense variants: 491 observed, 525.46 expected, observed/expected ratio (o/e) 0.93, 90% interval 0.87 to 1.01. Synonymous variants: 180 observed, 190.44 expected, observed/expected ratio (o/e) 0.95, 90% interval 0.84 to 1.07.
Homologues: Orthologues: chimpanzee SLC16A7 (100% identical), macaque SLC16A7 (94% identical), rabbit SLC16A7 (85% identical), guinea pig SLC16A7 (84% identical), dog SLC16A7 (82% identical), pig SLC16A7 (82% identical), mouse Slc16a7 (73% identical), rat Slc16a7 (72% identical), tropical clawed frog slc16a7 (70% identical), zebrafish SLC16A7 (60% identical), Drosophila melanogaster CG13907 (28% identical), Drosophila melanogaster Sln (28% identical), and 11 more. Paralogues in human: SLC16A1 (60% identical), SLC16A3 (43% identical), SLC16A8 (42% identical), SLC16A11 (31% identical), SLC16A6 (30% identical), SLC16A5 (29% identical), SLC16A12 (29% identical), SLC16A13 (29% identical), SLC16A14 (26% identical), SLC16A4 (25% identical), SLC16A10 (25% identical), SLC16A9 (24% identical), and 1 more.
Diseases named in the same sentence as SLC16A7 in open-access papers:
SLC16A7 is named in the same sentence as 89 diseases in open-access papers, as found by Europe PMC text mining. Sharing a sentence is not in itself a finding about the gene and the disease. The quoted sentences say what the papers report.
prostate carcinoma (15 papers, 2011 to 2024). A carcinoma that arises from epithelial cells of the prostate gland. "The study discovered that the localization of SLC16A7 to peroxisomes is linked to the malignant transformation of prostate cancer, as determined by assessing intracellular SLC16A7 expression." (PMID 39669362, 2024). "Studies of SLC16A7 have focused on prostate cancer and are associated with the malignant transformation of prostate cancer cells." (PMID 34424811, 2021). "SLC16A7 is not limited to prostate cancer, it has also been detected in various tumor cells, including those of lung and colon cancer." (PMID 39669362, 2024). "The putative presence of monocarboxylate transporters SLC16A1 (MCT1) and SLC16A7 (MCT2) is only based on immunoblotting of purified rat liver peroxisomes or immunocolocalisation in prostate cancer cells." (PMID 32266253, 2020). "SLC16A7 is significantly overexpressed in malignant prostrate tumors, suggesting that it may represent a biomarker of prostate cancer." (PMID 30328513, 2019). "Therefore, we postulate that a combination of epigenetic changes and oncogenic signalling pathways converge on SLC16A7/MCT2 in prostate cancer cells to effect isoform switching and protein over-expression in PCa tumours." (PMID 26035357, 2015). "SLC16A7 (also known as monocarboxylate transporter protein 2, MCT2) is mainly located in the peroxisomes of prostate cancer cells and interacts with Pex19 via the peroxidase transport mechanism." (PMID 30328513, 2019). "In this study we propose a rationale for the increase of MCT2 expression through an integrative analysis of epigenetic, transcriptome and protein level data from prostate cancer tissue and unveil a link between SLC16A7/MCT2 and major oncogenic pathways in prostate cancer." (PMID 26035357, 2015). "Also, the impact of MCT2 inhibition in PCa cells is still unknown and links between SLC16A7/MCT2 and major prostate cancer drivers such as Androgen Receptor (AR) ETS-related genes (ERG) have not previously been studied." (PMID 26035357, 2015).
colorectal cancer (5 papers, 2015 to 2025). A primary or metastatic malignant neoplasm that affects the colon or rectum. "A sub-analysis by KEGG signalling pathways revealed that SLC16A7 co-expressed genes are grouped in pathways associated with PCa, colorectal cancer, renal cell carcinoma, leukemia, melanoma, glioma and mTOR signalling pathway among others." (PMID 26035357, 2015).
prostate tumour (5 papers, 2011 to 2020). "These methylation changes are associated with differential expression in prostate tumours of an SLC16A7/MCT2 isoform that has an alternative 5′-UTR sequence containing alternative translation control elements." (PMID 26035357, 2015). "Together these findings suggest that selective methylation and demethylation occurs in prostate tumours at two distinct promoter regions within the SLC16A7/MCT2 locus, resulting in expression of an alternative isoform containing a different set of 5′-UTR translation signals." (PMID 26035357, 2015).
melanoma (4 papers, 2015 to 2025). A malignant, usually aggressive tumor composed of atypical, neoplastic melanocytes. "Investigating negative-regulated target genes, we found eight genes (ANKRD13C, ARL5A, ATL3, PAWR, PDCD6IP, SLC16A7, TFAM, UBP1) presenting a significant inverse correlation with miR-181a/b expression also in melanoma A375 sensitive cells." (PMID 33670365, 2021).
gastric cancer (3 papers, 2015 to 2024). A primary or metastatic malignant neoplasm involving the stomach. "COL4A1, SLC16A7 or IRAK1 are prognostic biomarkers in gastric cancer." (PMID 39669362, 2024). "Here, we combined patient clinicopathological data with COL4A1, SLC16A7 and IRAK1 to create a predictive nomogram for gastric cancer." (PMID 39669362, 2024). "Initially, we developed a gene signature related to lactylation to forecast the outcome of stomach cancer by analyzing genes with varying expressions, such as COL4A1, SLC16A7, and IRAK1." (PMID 39669362, 2024).
hepatocellular carcinoma (3 papers, 2022 to 2023). A malignant tumor that arises from hepatocytes. "Though in this paper, no experiments were performed to prove this reciprocal relationship of MCT2 (SLC16A7) and MCT4 (SLC16A3), this evidence from hepatocellular carcinoma might explain similar observations for Ovarian cancer and could be further validated in future using in vitro experiments." (PMID 37934721, 2023).
glioma (2 papers, 2015 to 2022). A benign or malignant brain and spinal cord tumor that arises from glial cells (astrocytes, oligodendrocytes, ependymal cells). "The correlation of SLC16A7/MCT2 expression with these oncogenic signalling molecules in CRC, glioma and PCa indicates an association between oncogenic pathways and SLC16A7 gene expression." (PMID 26035357, 2015).
Hypertension (2 papers, 2023 to 2025). The presence of chronic increased pressure in the systemic arterial system. "In contrast, hypertension shows that genes like SLC16A7, SPX, and PAX8 are less central, indicating they play a reduced role in the vascular and kidney networks." (PMID 40909129, 2025).
Cachexia (1 paper, 2022). Severe weight loss, wasting of muscle, loss of appetite, and general debility related to a chronic disease. "Furthermore, we detected the mRNA expression of lactate transporters Slc16a1 (in muscle), Slc16a5, and Slc16a7 (in liver) and found that the levels of all three lactate transporters were upregulated in the cachexia group compared with the NC group, and the 2-DG treatment reversed this change." (PMID 36230949, 2022).
Crohn disease (1 paper, 2009). A gastrointestinal disorder characterized by chronic inflammation involving all layers of the intestinal wall, noncaseating granulomas affecting the intestinal wall and regional lymph nodes, and transmural fibrosis. "A dense cluster of significant associations for Crohn's disease and HDL cholesterol is located in the monocarboxylate transporter 2 gene (SLC16A7, also known as MCT2), a ubiquitously expressed transporter that imports and exports lactate and pyruvate." (PMID 19161620, 2009).
tumor (54 papers, 2011 to 2026). "Elevated MCT2 (SLC16A7) levels were associated with increased expression of interleukin-1β (IL-1β) and lipocalin-2 (LCN2), both of which are linked to tumour progression and adverse outcomes." (PMID 41154605, 2025). "In order to explore the spread of lactic acid in tumor tissues, we conducted western blot and immunohistochemistry analysis to identify the presence of lactic acid and SLC16A7 in neighboring and tumor tissues." (PMID 39669362, 2024). "Expression of the SLC16A7 gene was observed in the tumor sample, as well as in patient-derived cell lines Gbl13 and Gbl17." (PMID 39126040, 2024). "To further study the effects of lactate on immune cells in the tumor microenvironment in vitro, we collected the supernatants of tumor cells from the blank control group and the SLC16A7 knockdown group to culture M0 macrophages." (PMID 39669362, 2024). "When lactic acid from tumor cells is transported to the tumor microenvironment through the lactate transporter SLC16A7, it can induce the conversion of M0 macrophages to the M2 type, suppressing the body’s immune function." (PMID 39669362, 2024). "LAGs like SLC16A8, SLC16A1, and LDHB have a higher methylation ratio in tumor tissue than in normal tissue; a lower methylation ratio of SLC16A7 and SLC16A3 is noticed in that comparison." (PMID 37122693, 2023). "Among all tumor types in TCGA, the most common mutated genes are HIF1A and SLC16A7, which accounts for 21% in all samples." (PMID 37122693, 2023). "For instance, SLC16A7 that mediates lactate homeostasis in cancer cells, and lactate has emerged as a critical regulator of tumor progression, inflammation, and angiogenesis." (PMID 31311925, 2019). "The Gb75t tumor sample represented a heterogeneous mixture of well-defined cell populations and included several types of astrocyte-like cells, SLC16A7+ or neural-like cells, and tumor microenvironment cells (micro- and macroglia, dendritic cells, and regulator T-lymphocytes)." (PMID 39126040, 2024). "Analysis of methylation profiling from a large cohort of PCa tumours (n = 304) showed that demethylation at the internal SLC16A7/MCT2 promoter region and hypermethylation at the upstream promoter is a recurrent and significant change in PCa tumours (Wilcox test p < 0.001)." (PMID 26035357, 2015). "Similarly, the level of SLC16A7 in the tumor tissue is greater than in the normal tissue." (PMID 39669362, 2024). "We found that the genes co-expressed with SLC16A7/MCT2 were functionally clustered in the categories of regulation of cell migration, response to wounding, inflammatory response, angiogenesis and apoptosis, all considered relevant for tumor progression and development." (PMID 26035357, 2015). "It has been repeatedly observed that glucose transporter GLUT1/SLC2A1 and lactic acid transporter MCT1/SLC16A1, MCT2/SLC16A7, MCT4/SLC16A3 are upregulated in multiple tumor types and participate in tumor genesis and development." (PMID 38396064, 2024). "In the Gbl13 sample (5 p), SLC16A7+ (or mesenchymal-like) cells and FOXN4+ cells were the major subpopulations of tumor cells, while neuronal cells and astrocytes were missing." (PMID 39126040, 2024). "Further, we examined the promoter methylation levels of DELMRGs and found that several genes (such as OAS2, KALRN, SLC16A7, PER2) had significantly lower methylation levels in tumor samples, while several genes (SLC6A3, CDO1, and SERPINC1) were significantly higher methylated." (PMID 37795453, 2023). "Importantly, genes co-expressed with SLC16A7/MCT2 in human tumours also clustered in oncogenic-related pathways (e.g. PI3K, EGFR, KRAS) and effectors of these signalling pathways were found to bind at the SLC16A7/MCT2 gene locus (e.g. MYC, EGR1, PRDM1)." (PMID 26035357, 2015). "In a cohort of four PCa tumours with matched non-malignant tissue we found two differentially methylated regions (DMRs) at the SLC16A7 locus." (PMID 26035357, 2015).
tumor (continued). "Conversely, the expression of SLC16A1 and SLC16A7 genes —encoding MCT1 and MCT2 lactate transporters, respectively—as well as of GJA1 (data not shown) encoding connexin 43 and responsible of lactate diffusion, does not differ between the two tumour subtypes." (PMID 37198319, 2023). "We also found that Cancer Cells interact with ITGB1 expressed in Fibroblasts, Endothelial Cells, SLC16A7 + Cells, FOXN4 + Cells, Basal Cells, GMP Cells, Monocytes, and NKT Cells through angiogenic signal molecules (VEGFA), which may stimulate tumor growth and metastasis." (PMID 36401283, 2022). "These alternative isoforms of SLC16A7/MCT2 contain identical coding sequences and differ only in their 5′-UTR sequences, analysis of which revealed key differences in motifs governing translational mechanisms between the isoforms expressed in tumour and benign prostate samples." (PMID 26035357, 2015). "There was no significant change in MCT2 protein expression between AR blockade (Degarelix) treated and untreated PCa tumours, suggesting that any AR signalling effects on specific SLC16A7/MCT2 isoforms do not impact on total MCT2 protein levels in the context of human PCa tumours." (PMID 26035357, 2015). "MCT2 (SLC16A7, p = 0.565) and MCT4 (SLC16A3, p = 0.438) showed no differential expression between HPV−ve and HPV+ve HNSCC; MCT1 expression (SCL16A1) however, was significantly elevated in HPV−ve tumours (p = 0.012), suggesting a potential tumour subtype-specific, metabolic target." (PMID 30655616, 2019).
cancer (48 papers, 2011 to 2025). A tumor composed of atypical neoplastic, often pleomorphic cells that invade other tissues. "Monocarboxylate transporter 2 (MCT2) is a major high-affinity pyruvate transporter encoded by the SLC16A7 gene, and is associated with glucose metabolism and cancer." (PMID 34638954, 2021). "In addition, we also illustrated that CHK1, CDK1, and PLK1 were associated with SLC16A7 in MDA-MB-231 and A549 cancer cells, providing a 75% validation ratio among four selected candidates." (PMID 31311925, 2019). "Lactate can be transported away from cancer cells through MYC-activated MCT1 (SLC16A1 solute carrier family 16 member 1 aliase) and MCT2 (SLC16A7 solute carrier family 16 member 7 aliase) channels." (PMID 37450923, 2024). "Interestingly, oncogenic KRAS mutations were shown to increase glucose uptake in cancer cells and lactate production through upregulation of glycolytic genes encoding glucose transporter SLC2A1/GLUT1 and the monocarboxylate transporters SLC16A1/MCT1, SLC16A7/MCT2, and SLC16A3/MCT4." (PMID 34003553, 2021). "miR-199b-5p targets solute carrier transporters (SLC1A2/EAAT2 in astrocytes and SLC38A2/SNAT2 and SLC16A7/MCT2 in neurons) to hijack the neuron–astrocyte metabolic coupling, leading to extracellular retention of these metabolites and promoting cancer cell growth." (PMID 38811525, 2024). "A significant decrease in the transcriptional level was observed for SLC16A7 in the cancer tissues, while a non-significant decrease persisted in the case of SLC16A8." (PMID 37934721, 2023). "Compared to MCT1 and MCT4, MCT2/SLC16A7 and MCT3/SLC16A8 are less often expressed in cancers." (PMID 28107190, 2017).
neurodegenerative disease (1 paper, 2026). A disorder of the central nervous system characterized by gradual and progressive loss of neural tissue and neurologic function. "Beyond its role in energy supply, MCT2 (encoded by SLC16A7) has recently drawn attention for its involvement in neurological and neurodegenerative diseases." (PMID 41491598, 2026).
SLC16A7 also shares sentences with these, for which no sentence is quoted: breast carcinoma (11 papers); Cognitive impairment (6); Alzheimer disease (4); amnesia (4); lung carcinoma (4); Stroke (4); breast tumour (3); Cerebral ischemia (3); colon cancer (3); epilepsy (3); glaucoma (3); Hyperglycaemia (3); Burkitt lymphoma (2); cognitive decline (2); colorectal tumour (2); cortical dysplasia (2); diffuse large B-cell lymphoma (2); glioblastoma (2); hypoglycaemia (2); ischemia (2); memory impairment (2); neurological diseases (2); ovarian cancer (2); prostate intraepithelial neoplasia (2); renal cell carcinoma (2); adenocarcinoma (1); adenoma (1); adrenocortical tumors (1); age-related macular degeneration (1); brain injury (1).
A further 46 diseases each share a sentence with SLC16A7 in 1 paper.